ZNF300 (zinc finger protein 300)
Description:
Has a transcriptional repressor activity.
Tractability: PROTAC: ubiquitination databases record sites on it.
Gene: Protein-coding gene on chromosome 5 (150,894,392 to 150,904,983, reverse strand). Ensembl gene ENSG00000145908.
Subcellular location: Nucleus
Subcellular location (Human Protein Atlas): Nucleoplasm; Nuclear bodies; Nucleoli; Nucleoli rim
Pathways (Reactome):
Gene expression (Transcription): Generic Transcription Pathway
Gene Ontology:
Molecular function: DNA-binding transcription activator activity, RNA polymerase II-specific; protein binding; sequence-specific DNA binding; DNA-binding transcription factor activity, RNA polymerase II-specific; RNA polymerase II cis-regulatory region sequence-specific DNA binding
Biological process: positive regulation of transcription by RNA polymerase II; regulation of transcription by RNA polymerase II; regulation of DNA-templated transcription
Cellular component: nucleoplasm; nucleus; nuclear lumen
Genetic constraint (gnomAD): Loss-of-function variants: 10 observed, 18.1 expected, observed/expected ratio (o/e) 0.55, 90% interval 0.34 to 0.94. The upper end of that interval is the gene's LOEUF score, 0.94, which puts it in group 3 of 6, group 1 being the genes least tolerant of losing a copy. Missense variants: 662 observed, 750.59 expected, observed/expected ratio (o/e) 0.88, 90% interval 0.83 to 0.94. Synonymous variants: 237 observed, 253.59 expected, observed/expected ratio (o/e) 0.93, 90% interval 0.84 to 1.04.
Homologues: Orthologues: chimpanzee ZNF300 (99% identical), macaque ZNF300 (98% identical), rabbit ZNF300 (86% identical), pig ZNF300 (86% identical). Paralogues in human: ZNF630 (58% identical), ZNF182 (52% identical), ZNF484 (52% identical), ZNF782 (50% identical), ZNF41 (49% identical), ZNF33B (48% identical), ZNF175 (48% identical), ZNF605 (47% identical), ZNF658 (47% identical), ZNF568 (46% identical), ZNF585B (45% identical), ZNF334 (45% identical), and 164 more.
Diseases named in the same sentence as ZNF300 in open-access papers:
ZNF300 is named in the same sentence as 31 diseases in open-access papers, as found by Europe PMC text mining. Sharing a sentence is not in itself a finding about the gene and the disease. The quoted sentences say what the papers report.
leukemia (3 papers, 2014 to 2020). A malignant (clonal) hematologic disorder, involving hematopoietic stem cells and characterized by the presence of primitive or atypical myeloid or lymphoid cells in the bone marrow and the blood. "As a typical member of KRAB-ZNFs, dysregulation of ZNF300 contributes to multiple pathologies such as leukemia and cancer." (PMID 28670441, 2017). "Dysregulation of ZNF300 contributes to multiple pathologies including leukemia and cancer." (PMID 28670441, 2017).
lung carcinoma (3 papers, 2020 to 2025). "Because only age, sex and stage were listed in Broet‐Lung, we used the data from Larsen‐Lung to analyse the association of ZNF300 with the clinical characteristics of lung cancer patients." (PMID 33078469, 2020). "The most dominantly enriched gene in PDOs from oxaliplatin-resistant tumors was ZNF300 (log2 fold change 21, FDR <0.001), which has previously been associated with platinum resistance in lung cancer cells." (PMID 41280668, 2025). "Interestingly, two ZNF300 datasets of lung cancer appeared in the outlier analysis (Broet‐Lung and Larsen‐Lung)." (PMID 33078469, 2020). "Additionally, ADH1B, ZNF300, GPR161, and RDH11 were presented as the novel regulatory genes in lung injury and lung cancer." (PMID 39940682, 2025).
acute promyelocytic leukemia (2 papers, 2016 to 2022). An aggressive form of acute myeloid leukemia (AML), characterized by arrest of leukocyte differentiation at the promyelocyte stage, due to a specific chromosomal translocation t(15;17) in myeloid cells. "ZNF300 promoter activity was found to be regulated by PU.1 transcription factor in acute promyelocytic leukemia." (PMID 27871300, 2016).
chronic myeloid leukemia (2 papers, 2013 to 2020). "Finally, ZNF300 expression varies in different types of leukaemic blasts in the bone marrow samples of acute myeloid leukemia (AML) and chronic myeloid leukemia (CML) patients." (PMID 24294107, 2013).
gastric cancer (2 papers, 2021 to 2022). A primary or metastatic malignant neoplasm involving the stomach. "The results suggested that the expression of ELK3 and SP6 is increased in gastric cancer, and the expression of ZNF300 and MEF2B is down-regulated in gastric cancer." (PMID 34233659, 2021). "In addition, using The Human Protein Atlas (HPA) to analyze the protein expression of hub TFs, ELK3 immunohistochemical staining intensity in normal tissues is lower than gastric cancer tissues, while ZNF300 and MEF2B are higher than gastric cancer tissues." (PMID 34233659, 2021).
ovarian carcinoma (2 papers, 2014 to 2016). A malignant neoplasm originating from the surface ovarian epithelium. "Given that ZNF300 is up-regulated in cancer, and promotes inflammation and metastasis, the repression of ZNF300P1 associated with methylation in ovarian cancer make it unlikely to be functioning as an miRNA decoy." (PMID 24393131, 2014). "In addition, a pseudo-gene of the human ZNF300, ZNF300P1, which shares 89% identity with ZNF300, is a long-intergenic non-coding RNA that is frequently methylated in ovarian cancer, indicating a potential role for ZNF300P1 expression in regulating ovarian cancer cell metastasis." (PMID 27982099, 2016).
preeclampsia (2 papers, 2018 to 2024). Preeclampsia is a hypertensive disorder of pregnancy that is characterized by new-onset hypertension with proteinuria presenting after 20 weeks of gestation, and depending on mild or severe forms may initially present with severe headache, visual disturbances, and hyperreflexia. "Hypermethylation of the ZNF300 gene in placenta is associated with intrauterine growth restriction in twin pregnancies at term, as well as preeclampsia at term." (PMID 39152463, 2024). "Increased expression of ZNF300 in females may function as a competitor of EGR1 binding sites, leading to reduced rates of preeclampsia." (PMID 29335024, 2018).
anaplastic oligodendroglioma (1 paper, 2020). A WHO grade III oligodendroglioma with focal or diffuse malignant morphologic features (prominent nuclear pleomorphism, mitoses, and increased cellularity). "Additionally, the expression of ZNF300 in anaplastic oligodendroglioma, glioblastoma, skin basal cell carcinoma, invasive ductal breast carcinoma and invasive lobular breast carcinoma was significantly higher than that of the corresponding normal tissues." (PMID 33078469, 2020).
cervical cancer (1 paper, 2017). A primary or metastatic malignant neoplasm involving the cervix. "For instance, ZNF268b2 expression is associated with cervical cancer while ZNF300 expression correlates to blood cell maturation and leukemogenesis possibly by affecting terminal differentiation of blood cells." (PMID 28670441, 2017). "In addition, ZNF300 has been shown to act as a signaling molecule to enhance NF-κB signaling and promote cervical cancer cell proliferation." (PMID 28670441, 2017).
Crohn disease (1 paper, 2014). A gastrointestinal disorder characterized by chronic inflammation involving all layers of the intestinal wall, noncaseating granulomas affecting the intestinal wall and regional lymph nodes, and transmural fibrosis. "Previously, ZNF300 was shown to correlate with Crohn's disease and 5q-syndrome." (PMID 25485965, 2014).
hepatocellular carcinoma (1 paper, 2020). A malignant tumor that arises from hepatocytes. "Since ZNF300 was one of the three methylated genes identified in the plasma cell‐free DNA (cfDNA) of hepatocellular carcinoma as compared to liver tissue DNA, it can be used as a biomarker for early detection and high‐risk screening of hepatocellular carcinoma." (PMID 33078469, 2020).
lung adenocarcinoma (1 paper, 2020). A carcinoma that arises from the lung and is characterized by the presence of malignant glandular epithelial cells. "Additionally, ZNF300 was displayed to be associated with the poor OS of patients with lung adenocarcinoma, confirming that ZNF300 mediated the malignancy of NSCLC." (PMID 33078469, 2020).
myelodysplastic syndrome (1 paper, 2014). A clonal hematopoietic disorder characterized by dysplasia and ineffective hematopoiesis in one or more of the hematopoietic cell lines. "In addition, ZNF300 was downregulated during embryonic stem cell differentiation in vitro and associated with 5q-syndrome, a distinct subtype of primary myelodysplastic syndrome (MDS) defined by interstitial deletion of chromosome 5q31-33." (PMID 25485965, 2014).
cancer (12 papers, 2014 to 2025). A tumor composed of atypical neoplastic, often pleomorphic cells that invade other tissues. "While ZNF300 has been previously associated with therapy resistance in several cancer types, its potential role in oxaliplatin resistance in CRC merits further investigation." (PMID 41280668, 2025). "Evidence of hypermethylation at the CpG island associated with ZNF300P1 was observed in both cancer cell lines, however hypermethylation of neighboring CpG islands (ZNF300 and GPX3) was only observed in A2780 cells." (PMID 24393131, 2014). "ZNF300, CSMD1, and CADM2 have been implicated in cancer cell proliferation, migration, and invasion, features mirrored by the invasive, immunologic, and angiogenic properties of placental cells." (PMID 40312437, 2025). "Reports in tumors indicated that ZNF300 can promote the progression of cancer cells by activating NF-κB and MAPK pathways to induce tumor cell proliferation, invasion, and drug resistance." (PMID 34233659, 2021). "The available data point toward ZNF300 contribution to immune cell development, as well as to carcinogenesis and cancer-related inflammatory signaling." (PMID 33672287, 2021). "Furthermore, with the overexpression of ZNF300, the MAPK/ERK-controlled genes became downregulated, while the genes implicated in the cell cycle (p15, p27) and cancer stemness (NANOG, OCT4) became upregulated." (PMID 33672287, 2021). "In addition to hematologic malignancies, ZNF300 gene overexpression enhanced growth and metastasis of cancer cells through activating NF-κB pathway in cervical cancer." (PMID 33219204, 2020). "Additionally, overexpression of ZNF300 stimulated cancer cell proliferation in vitro and significantly enhanced tumor development and metastasis in a xenograft mouse model." (PMID 27907911, 2016). "Comparison of signaling pathway affected by ZNF300 in carcinoma cells and leukemic cells may provide more information." (PMID 25485965, 2014). "Although ZNF300 has not previously been associated with IUGR, its strong role in cancer development supports its potential to impact fetal growth." (PMID 27330572, 2016).
tumor (7 papers, 2014 to 2025). "In the clinical specimens, a high level of ZNF300 expression was linked to more advanced and aggressive tumor phenotypes, as well as shorter survival." (PMID 33672287, 2021). "ZNF300, a novel zinc finger protein identified specifically in humans, has been shown to promote tumor development by modulating the NF-κB pathway." (PMID 40599863, 2025). "Of note, the bioinformatics analysis indicated elevated ZNF300 expression in other highly aggressive tumor types, including anaplastic oligodendroglioma, glioblastoma, skin basal cell carcinoma, and invasive breast carcinomas." (PMID 33672287, 2021). "The functional assays indicated that ZNF300 promotes cell proliferation, colony formation in vitro, as well as tumor growth in a xenograft mouse model." (PMID 33672287, 2021). "ZNF300 promotes aggressive growth of tumour cells correlating to poor prognosis of patients with NSCLC." (PMID 33078469, 2020). "Furthermore, ZNF300 induces the NF-kB pathway, in turn inducing IL-6 and IL-8, potentially exacerbating inflammation and promoting tumor metastasis." (PMID 24393131, 2014). "Specifically, ZNF300 stimulated MAPK/ERK signaling, decreased p21 and p27, and mediated the secretion of IL-6 and IL-8, known for promoting inflammation and tumor progression." (PMID 33672287, 2021). "Several limitations exist in this study; firstly, since the collection of tumour specimens from patients who present the chemoresistant phenotype is difficult, the current research could not provide the clinical evidence of the ZNF300 association with cisplatin‐induced chemoresistance." (PMID 33078469, 2020). "The apoptosis of A549‐ZNF300 and A549/DDP‐shZNF300‐NC cells induced by cisplatin was significantly lower than that of A549‐ZNF300‐NC and A549/DDP‐shZNF300 cells, demonstrating that ZNF300 mediated the chemoresistance of NSCLC, which was confirmed in the subcutaneous tumour xenograft model." (PMID 33078469, 2020). "Meanwhile, ZNF300 might activate CDK1 through inhibition of WEE1 and MYT1 and modulation of the MYC/AURKA/BORA/PLK1 axis to promote the tumour cells to overcome G2 arrest and enter the M phase to avoid the apoptosis induced by chemotherapeutic drugs." (PMID 33078469, 2020). "The immunoblotting showed that ZNF300‐flag, used as bait, could bind to E2F3, indicating that ZNF300 might interact with E2F3 to function in the chemoresistance and aggressive behaviour of tumour cells." (PMID 33078469, 2020). "ZNF300 expression was higher in the desmoid tumours than in the normal tissues, but its function is still unknown." (PMID 33078469, 2020).
infection (1 paper, 2020). The state of being infected such as from the introduction of a foreign agent such as serum, vaccine, antigenic substance or organism. "Firstly, we successfully established SKM-1 cells stably overexpressing ZNF300 by Lv-ZNF300 infection, which was determined by fluorescence, RQ-PCR, and western blot." (PMID 33219204, 2020).
ZNF300 also shares sentences with these, for which no sentence is quoted: acute myeloid leukemia (1 paper); cardiac hypertrophy (1); congenital cataracts (1); dilated cardiomyopathy (1); glioblastoma (1); hematologic malignancies (1); human papillomavirus infection (1); inflammatory bowel disease (1); intrauterine growth restriction (1); invasive ductal breast carcinoma (1); invasive lobular breast carcinoma (1); neuropathy (1); renal failure (1); skin basal cell carcinoma (1); uterine cancer (1).